NOTCH1 (notch receptor 1)
Diseases named in the same sentence as NOTCH1 in open-access papers (continued):
Sharing a sentence is not in itself a finding about the gene and the disease.
diffuse gastric adenocarcinoma (1 paper, 2020). An adenocarcinoma arising from the stomach. "Chen showed that the expression of Notch1 was also higher in cancer tissues, since the expression in gastric intestinal type adenocarcinoma and diffuse gastric adenocarcinoma was 1.920 and 1.733 times respectively of that in patients with normal gastric tissue, respectively." (PMID 32028262, 2020).
diffuse intrinsic pontine glioma (1 paper, 2023). A neuroglial tumor that arises from the middle portion of the brain stem. "Similarly, in diffuse intrinsic pontine glioma, the expression of critical oncogenic genes such as SOX2 and NOTCH1 is regulated by super-enhancers, and treatment with super-enhancer inhibitors reduces diffuse intrinsic pontine glioma cell proliferation in vitro and tumor progression in mouse models." (PMID 38135679, 2023).
Dowling-Degos disease (1 paper, 2020). A pigmentation disease characterized by a reticulate pattern of abnormally dark skin coloring, particularly in the body's folds and creases. "A recent approach was conducted to determine how POFUT1 missense mutations could impact NOTCH1 signaling (R240A, M262T, S356F and R366W) found in Dowling-Degos disease (DDD), an autosomal dominant genodermatosis." (PMID 32486426, 2020).
Down syndrome (1 paper, 2019). "In addition, Notch1 is overexpressed in the neurogenic and non-neurogenic regions of the brain in sporadic Alzheimer’s disease and adults with Down syndrome." (PMID 31770379, 2019).
endocrine cancers (1 paper, 2016). "Histone deacetylase (HDAC) activity is indispensable for EZH2-mediated gene repression, and HDAC inhibitors can induce NOTCH1 expression in some endocrine cancers, indicating the relevance of EZH2 and NOTCH1 and their convergence at HDAC." (PMID 27049834, 2016).
endometrial adenocarcinoma (1 paper, 2016). "The consistent increase in mir-34a level in EAC, accompanied by a decrease in NOTCH1 and DLL1 levels, suggests that mir-34a may serve as a molecular marker of neoplastic transformation in endometrial adenocarcinoma." (PMID 27039384, 2016). "Furthermore, our study is the first to identify a correlation between mir-34a and its target genes NOTCH1 and DLL1 in endometrial adenocarcinoma." (PMID 27039384, 2016).
endometrial endometrioid carcinoma (1 paper, 2022). "Concerning endometrial endometrioid carcinoma, cases presenting genes with alterations in PTEN (71%), PIK3CA (60%), and NOTCH1 (43%) were the most observed." (PMID 36010253, 2022).
fetal hydrops (1 paper, 2025). "Although in mouse models, there is a demonstrated relationship between NOTCH1 mutations and defective lymphatic system development, review of the current literature yields no documentation of an association between NOTCH1 pathogenic variants and fetal hydrops." (PMID 40926891, 2025).
fibroepithelial polyp (1 paper, 2025). A polypoid lesion composed of fibrous tissue and epithelium. "The other mutations found in our case (DNMT3A, C8B, TET2, SDHA, ARID1B, NOTCH1, OR5L1, and KDM6A) do not have a known association with the formation of fibroepithelial polyps." (PMID 40936011, 2025).
focal segmental glomerulosclerosis (1 paper, 2014). A renal disorder characterized by sclerotic lesions in the glomeruli. "It was reported that Notch1 was reactivated in kidney specimens from patients with DN and focal segmental glomerulosclerosis (FSGS) and that reactivation of Notch1 correlated with the development of proteinuria due to podocyte apoptosis." (PMID 25309512, 2014).
gastric intestinal type adenocarcinoma (1 paper, 2020). An adenocarcinoma of the stomach arising on a background of intestinal metaplasia. "Based on the dataset of DErrico, the expression of Notch1 in gastric intestinal type adenocarcinoma was also 2.247 times of that in normal tissue." (PMID 32028262, 2020).
gastric MALT lymphomas (1 paper, 2021). "The frequency of TNFAIP3, TET2, and NOTCH1 mutations in H. pylori negative gastric MALT lymphoma is similar to those seen in unselected gastric MALT lymphomas, whereas the previously reported TNFRSF14 alterations affecting gastric MALT lymphomas were absent in the current series." (PMID 34203889, 2021).
giant cell arteritis (1 paper, 2021). "Moreover, Notch1 protein was up-regulated on circulating CD4+ T cells in patients with giant cell arteritis compared to healthy controls." (PMID 33912195, 2021). "By analyzing gene expression in tissue from arteries of patients with giant cell arteritis and healthy individuals, Wey and colleagues found abundant expression of JAG1 and NOTCH1 in vasculitic arteries." (PMID 33912195, 2021).
glomus tumor (1 paper, 2014). A rare benign or malignant mesenchymal neoplasm arising from cells that resemble the modified smooth muscle cells of the glomus body. "Other reports, show an association of MIR143 gene with NOTCH1-3; suggesting that the mechanism of MIR143–NOTCH1-3 tumorigenesis is through oncogenic activation of NOTCH driven by the very strong MIR143 promoter in malignant glomus tumors." (PMID 25717438, 2014).
goblet cell adenocarcinomas (1 paper, 2023). "In appendiceal cancers, NOTCH1 gene mutations are identified in some cases of appendiceal goblet cell adenocarcinoma, mucinous adenocarcinomas of the appendix, and low-grade appendiceal mucinous neoplasms, and in some cases of appendiceal cancers, without further specification." (PMID 37509254, 2023).
Hashimoto thyroiditis (1 paper, 2025). An autoimmune disorder caused by the production of autoantibodies against thyroid tissue. "Similarly, Notch1 signaling can enhance the effector function of TGF-β-mediated Tregs, as evidenced by the treatment of Hashimoto’s thyroiditis with Xiaoying Daotan Tang." (PMID 41458964, 2025).
helminth infection (1 paper, 2010). "In line with the role of Treg cells in helminth infection, NOTCH1 has recently been shown to be involved in Treg function and to cooperate with TGFb for regulation of the FOXP3 promoter." (PMID 20807397, 2010).
hepatocellular adenoma (1 paper, 2018). A benign epithelial neoplasm arising from the hepatocytes. "Deletion of Notch2 in AKT/Yap-induced tumors switched the phenotype from ICC to hepatocellular adenoma-like lesions, while inactivation of Notch1 in hepatocytes did not result in significant histomorphological changes." (PMID 29545603, 2018). "Histological analysis showed that tumor-specific ablation of Notch1 did not change tumor morphology: indeed, ICC lesions were found throughout the liver and no hepatocellular tumors, including hepatocellular adenoma and HCC, were observed in both AKT/Yap/Cre and AKT/Yap/pCMV Notch1flox/flox mice." (PMID 29545603, 2018).
hereditary leiomyomatosis (1 paper, 2020). "Apart from epigenetic alterations, increased fumarate upon FH loss in hereditary leiomyomatosis and renal cell cancer (HLRCC) modulated NFE2-related factor 2, which promoted EMT via activation of NOTCH1." (PMID 32839493, 2020).
hydrops (1 paper, 2025). "This case of a NOTCH1 pathogenic variant is an important addition to the growing body of literature on nonimmune hydrops as well as the embryonic manifestations of this genetic defect." (PMID 40926891, 2025).
Hyperammonemia (1 paper, 2025). An increased concentration of ammonia in the blood. "This neuroprotective impact can be justified by lowering hyperammonemia, improving liver functions, in addition to its antioxidant effect, and suppression of TLR-4/Notch1/NF-κB inflammatory pathway." (PMID 40920270, 2025). "The Neuro-protective effect of Dapagliflozin was mediated through the reduction of hyperammonemia, the enhancement of hepatic functions, inactivation of TLR4/Notch1/NF-κB pathway, and apoptosis inhibition." (PMID 40920270, 2025).
Hyperinsulinemia (1 paper, 2013). An increased concentration of insulin in the blood. "Systemically-delivered NICD shRNA reversed the enhancing effect of NICD on PDX-1, as well as on hyperinsulinemia and hypoglycemia, suggesting that Notch1 could be a potential therapeutic target." (PMID 24705209, 2013).
hyperphosphatemia (1 paper, 2017). Abnormally high level of phosphate in the blood. "Secondly, in the late stage of DN, impaired renal function causes hyperphosphatemia which stimulates Notch1-RBP-Jk signaling pathway to induce the expression of target gene Msx2, resulting in osteogenic differentiation and mineralization of VSMCs." (PMID 29464183, 2017).
hyperplasia (1 paper, 2021). An abnormal increase in the number of cells in an organ or a tissue with consequent enlargement.
hypertrophic cardiomyopathy (1 paper, 2023). A condition in which the myocardium is hypertrophied without an obvious cause. "Then, to clarify the underlying signaling pathway regulated by PRMT1 in cardiac remodeling, we screened some potential signaling pathways that were relevant to cardiac contraction and hypertrophic cardiomyopathy, including p-GSK3β/GSK3β, p-ERK/ERK, p-AKT/AKT and NICD/Notch1." (PMID 37951845, 2023).
idiopathic pulmonary arterial hypertension (1 paper, 2025). A sporadic form of pulmonary arterial hypertension (PAH) characterized by elevated pulmonary arterial resistance leading to right heart failure. "In patients with idiopathic pulmonary arterial hypertension (IPAH) and the hypoxia/SU5416 (SUHx) rat model, Notch1 expression was markedly increased, particularly in pulmonary arterial endothelial cells." (PMID 40453665, 2025).
inflammatory breast carcinoma (1 paper, 2020). An advanced, invasive breast adenocarcinoma characterized by the presence of distinct changes in the overlying skin. "For example, Sdc-1 expression in inflammatory breast cancer is correlated with CD44, Notch-1, and Notch-3 expression, and siRNA knockdown of Sdc-1 results in a weaker CSC phenotype and reduced expression of Notch-1-4 and Hey1 in inflammatory breast cancer cells." (PMID 33102470, 2020).
insulinoma (1 paper, 2013). "We report here that overexpression of Notch1 intracellular domain (NICD), an activated form of Notch1, enhanced PDX-1 expression in both PDX-1 stable HEK293 cells and mouse insulinoma β-TC-6 cells, while NICD shRNA inhibited the enhancing effect." (PMID 24705209, 2013).
invasive carcinoma (1 paper, 2019). A carcinoma that is not confined to the epithelium, and has spread to the surrounding stroma. "This indicates that NOTCH1 inactivation is a relatively early event but still consistent with previous observations that suggest that NOTCH1 inactivation plays a key role in progression to invasive carcinoma of already initiated cells." (PMID 31427592, 2019).
IPEX syndrome (1 paper, 2023). "The remaining 13 patients have NOTCH1 mutation (n = 1); ALPS-Caspase10 (n = 1); CD137 deficiency (n = 1); interleukin-37 deficiency (n = 1); IPEX syndrome (n = 1); prolidase deficiency (n = 1); PRKCD deficiency (n = 1); MAGT1 deficiency (n = 1); and unspecified immune dysregulatory disease (n = 5)." (PMID 37559153, 2023).
keratoacanthoma (1 paper, 2021). A dome-shaped, rapidly growing skin lesion composed of well differentiated squamous cells. "Consistent with this, in our previously reported Onc3 screen, we noted that the frequency of Notch1 inactivation was decreased in cuSCC versus keratoacanthoma tissues, suggesting that Notch1 loss is not essential for cuSCC development." (PMID 33435458, 2021).
kidney inflammation (1 paper, 2022). "The results indicated that PGC-1α overexpression provides sufficient metabolic input and can reduce Notch1/Hes1 pathway activation, thereby alleviating AKI induced kidney inflammation, apoptosis and fibrosis." (PMID 35225153, 2022).
kidney injury (1 paper, 2024). Trauma to the kidney. "Ischemic kidney injury has been shown to upregulate NOTCH1, which regulates cell proliferation and regeneration." (PMID 38791999, 2024).
Kleefstra syndrome (1 paper, 2017). A genetic disorder characterized by intellectual disability, childhood hypotonia, severe expressive speech delay and a distinctive facial appearance with a spectrum of additional clinical features. "NOTCH1 functions in the development of the semilunar valves and cardiac outflow tract, and deletion of EHMT1 manifests distinct features of 9q subtelomeric deletion syndrome or Kleefstra syndrome." (PMID 28211529, 2017).
large cell lung carcinoma (1 paper, 2012). "The same regulatory effects of SOX2 on the expression of WNT1, WNT2, NOTCH1 and c-MYC were also observed in the human large cell lung carcinoma cell line H460 with SOX2 silencing.This finding indicates a universal regulatory mechanism of SOX2 on the oncogene network of both human lung cell lines." (PMID 22615765, 2012).
Leukoencephalopathy (1 paper, 2024). This term describes abnormality of the white matter of the cerebrum resulting from damage to the myelin sheaths of nerve cells. "This case provides further data on a new diagnostic entity, i.e., NOTCH1-related leukoencephalopathy." (PMID 38474113, 2024). "We describe five years of follow-up and review the current literature on NOTCH1-related leukoencephalopathy." (PMID 38474113, 2024).
Lipedema (1 paper, 2023). Disorder of adipose tissue characterized by symmetric and bilateral enlargement of the lower extremities due to abnormal deposition of subcutaneous fat often in obese women. "Our data show a decrease in NOTCH 1–4 gene and Delta 1 and 4 in HUVECs treated with CM from lipedema adipocytes compared to untreated and treated HUVECs with CM from healthy adipocytes." (PMID 37686378, 2023).
Loeys-Dietz syndrome (1 paper, 2022). Loeys-Dietz syndrome is a rare genetic connective tissue disorder characterized by a broad spectrum of craniofacial, vascular and skeletal manifestations with four genetic subtypes described forming a clinical continuum. "With regards to mechanoregulation, TGF-β receptors (implicated in Loeys-Dietz syndrome) and Notch1 (impaired signaling seen in dilated autografts) are implicated." (PMID 35224059, 2022).
Lymphadenopathy (1 paper, 2023). Enlargement (swelling) of a lymph node. "Splenomegaly and hepatomegaly were less prevalent compared to lymphadenopathy in our study group, but still, a higher prevalence could be observed in those with NOTCH1 mutation (59%), compared to those with normal results (24%) or CNVs (38%)." (PMID 37623489, 2023). "Notably, we found a significant association between lymphadenopathy and the presence of NOTCH1 mutation (p < 0.001), observed in more than 78% of patients." (PMID 37623489, 2023).
lymphatic diseases (1 paper, 2023). "Together, our data reveal a requirement for VEGFR3 and NOTCH1 signaling in the development of button junctions during postnatal development and may hold clinical relevance to lymphatic diseases with impaired VEGFR3 signaling." (PMID 37454290, 2023).
Lymphatic Metastasis (1 paper, 2023). Transfer of a neoplasm from its primary site to lymph nodes or to distant parts of the body by way of the lymphatic system. "According to all above, we came to a conclusion that NOTCH1 was indispensable for MIR503HG-mediated VEGFC secretion in pRCC-associated lymphatic metastasis." (PMID 37416763, 2023).
Lynch syndrome (1 paper, 2022). An autosomal dominant hereditary neoplastic syndrome characterized by the development of colorectal carcinoma and a high risk of developing endometrial carcinoma, gastric carcinoma, ovarian carcinoma, renal pelvis carcinoma, and small intestinal carcinoma. "NOTCH1 was found only in the P and P-Lynch syndrome groups but not in the other groups, thus verifying the results of the pathway enrichment analysis." (PMID 35014770, 2022).
MELAS (1 paper, 2020). "However, by day 35, mRNA expressions of Notch receptor NOTCH1, NOTCH receptor ligands DLL1 and JAG1 as well as the downstream targets HEY1 and HES5 were significantly higher in day 35 MELAS compared to controls." (PMID 32170107, 2020).
meningitis (1 paper, 2021). A disorder characterized by acute inflammation of the meninges of the brain and/or spinal cord. "Notch1 signaling is reported to promote NSC/NPC proliferation but decrease neuronal differentiation during meningitis and spinal cord injury." (PMID 34239542, 2021).
microcephaly (1 paper, 2024). A congenital or acquired developmental disorder in which the circumference of the head is smaller than normal for the person's age and sex. "As premature neuronal differentiation of progenitor cells is a proposed mechanism of microcephaly, an increase in Notch1 may contribute to this phenomenon." (PMID 39602444, 2024).
microcystic adnexal carcinoma (1 paper, 2025). "Furthermore, microcystic adnexal carcinoma (MAC) has been found to frequently harbor mutations in PTEN and NOTCH1, which are absent in SEDC, providing an avenue for molecular differentiation." (PMID 40282903, 2025).
mitral atresia (1 paper, 2025). "Patients in Group 2, the mitral atresia group, carried variants in genes related to mitral atresia, including EP300, NOTCH1, and TTN." (PMID 41153298, 2025). "Patients in Group 2, the mitral atresia group, carried variants in the genes including EP300, NOTCH1, and TTN (mitral atresia), CREBBP, EP300, and NOTCH1 (hypoplastic left ventricle)." (PMID 41153298, 2025).
mucinous adenocarcinoma (1 paper, 2018). An invasive adenocarcinoma composed of malignant glandular cells which contain intracytoplasmic mucin. "NOTCH1 overexpression is only associated with rectal location and non-mucinous adenocarcinoma." (PMID 30380753, 2018). "Overexpression of POFUT1 and NOTCH1 is preferentially observed in non-mucinous adenocarcinoma histological type." (PMID 30380753, 2018).
mucinous tumors (1 paper, 2021). "Consistently, the protein abundance of Notch1 intracellular domain (NICD), the major activator of canonical Notch signaling pathway, as well as Notch effector HES1, were markedly increased in KLN mucinous tumors relative to non‐mucinous tumors, as evidenced by IHC staining and statistical analyses." (PMID 33439550, 2021).
mycosis fungoides (1 paper, 2022). Classical mycosis fungoides is the most common type of mycosis fungoides (MF), a form of cutaneous T-cell lymphoma, and is characterized by slow progression from patches to more infiltrated plaques and eventually to tumors. "The downregulation of miR-200c mediated by methylation is associated with the overexpression of Jagged1, which is responsible for Notch1 activation, hence the development of mycosis fungoides." (PMID 35408897, 2022). "Although there is no detection of DNA methylation at the Notch1 promoter, methylation of miR-200c has been observed in cases of mycosis fungoides." (PMID 35408897, 2022).
myoclonic epilepsy (1 paper, 2022). A group of epilepsy syndromes in which myoclonic seizures are a prominent feature. "Of the 89 patients with pathogenic and likely pathogenic NOTCH1 variants, 21 were reported in the context of syndromic disease including AOS (n=19), Shone complex (n=1) and 1 in a patient in whom congenital AS co-existed with myoclonic epilepsy and learning difficulties (no: 9, 13, 32, 43, 47, 62)." (PMID 35288444, 2022).
nephrotic syndrome (1 paper, 2021). A collection of symptoms that include severe edema, proteinuria, and hypoalbuminemia; it is indicative of renal dysfunction. "Besides, NOTCH1-rs3124591 is also significantly correlated with nephrotic syndrome risk and alteration in its sensitivity to hormone in Chinese population." (PMID 34257585, 2021).
non-alcoholic steatohepatitis (1 paper, 2025). "Specifically, ginsenoside Rg5 inhibits the activation of the Notch1 signaling pathway by upregulating the expression of Sirt1 protein, thereby suppressing hepatic lipid accumulation and fibrosis in non-alcoholic steatohepatitis (NASH)." (PMID 41226211, 2025).